SRSF1 (serine and arginine rich splicing factor 1)
Diseases named in the same sentence as SRSF1 in open-access papers (continued):
Sharing a sentence is not in itself a finding about the gene and the disease.
Alzheimer disease (4 papers, 2019 to 2025). A progressive, neurodegenerative disease characterized by loss of function and death of nerve cells in several areas of the brain leading to loss of cognitive function such as memory and language. "In the COVID-19 cohort with Alzheimer's disease, the serine- and arginine-rich splicing factor 1 is encoded by the downregulation of SRSF1." (PMID 37521843, 2022). "Research shows that SRSF1 promotes exon 10 inclusion during tau alternative splicing in Alzheimer's disease." (PMID 40585977, 2025).
Autoimmunity (4 papers, 2011 to 2025). The occurrence of an immune reaction against the organism's own cells or tissues. "Splicing factor SRSF1 has been recognized to affect autoimmunity and tissue inflammation through regulation of effector T cells." (PMID 40585977, 2025).
colon adenocarcinoma (4 papers, 2010 to 2022). "The splice factor SRSF1 has been shown to promotes Mnk2 splicing into Mnk2b instead of Mnk2a, and thereby enhance tumor proliferation in colon adenocarcinoma." (PMID 36418856, 2022). "Our study reveals a significant role of SRSF1-guided MKNK2a-MKNK2b splicing switch in the proliferation of colon adenocarcinoma, which is determined by SRSF1 phosphorylation and subcellular translocation." (PMID 33602301, 2021). "Consistent with electron microscopy data, we verified the critical role of TNPO3 on importing SRSF1 into nucleus of colon adenocarcinoma cells." (PMID 33602301, 2021). "Considering that enzyme-substrate relationship can be difference in various cell types, we initially explored whether those kinases could affect SRSF1 nucleus translocation in colon adenocarcinoma cells." (PMID 33602301, 2021). "In colon adenocarcinoma cells, SRSF1 is hyperphosphorylated due to elevated SRPK1/2 and decreased PP1α activity, resulting in SRSF1 nucleus shuttling." (PMID 33602301, 2021). "Additionally, the subcellular location of SRSF1, expression levels of SRPK1/2, as well as phosphorylation status of PP1α can all serve as independent prognostic predictors for the overall survival of colon adenocarcinoma." (PMID 33602301, 2021).
COVID-19 (4 papers, 2022 to 2023). A disease caused by infection with severe acute respiratory syndrome coronavirus 2. "We therefore concluded that HSP90AA1, HSPA9, and SRSF1 are pivotal genes in the co-morbidity of COVID-19 and ICM and have considerable diagnostic value." (PMID 37047484, 2023). "In this study, HSP90AA1, HSPA9, and SRSF1 were identified as markers for the co-pathogenesis of COVID-19 and ICM." (PMID 37047484, 2023). "We identified HSP90AA1, HSPA9, and SRSF1 as markers for the co-pathogenesis of ICM and COVID-19, and showed that co-pathogenesis of ICM and COVID-19 may be related to angiogenesis." (PMID 37047484, 2023). "Despite the failure of docking with SRSF1, the docking of vindesine and ON-01910 with HSP90AA1 and HSPA9 tentatively validated the feasibility of these drugs binding to the hub genes, indicating that vindesine and ON-01910 may be disease-specific agents of ICM and COVID-19." (PMID 37047484, 2023).
esophageal squamous cell carcinoma (4 papers, 2021 to 2023). Esophageal squamous cell carcinoma (ESCC) is a type of esophageal carcinoma (EC) that can affect any part of the esophagus, but is usually located in the upper or middle third. "Nevertheless, the biological mechanism underlying tumorigenesis of lncRNAs correlated with SRSF1 in esophageal squamous cell carcinoma (ESCC) remains elusive." (PMID 34099633, 2021). "LncRNA DGCR5 binds directly to serine-and arginine-rich splicing factor 1(SRSF1) to increase its stability, thereby stimulating the Mcl-1 alternative splicing event to promoting the occurrence of esophageal squamous-cell carcinoma in vivo." (PMID 34888249, 2021).
heart failure (4 papers, 2014 to 2025). Inability of the heart to pump blood at an adequate rate to meet tissue metabolic requirements. "On the contrary, ablation of SRSF1 in cardiomyocytes, which have low regenerative potential, resulted in heart failure and death." (PMID 36759613, 2023).
HIV-1 infection (4 papers, 2008 to 2023). The type species of lentivirus and the etiologic agent of acquired immunodeficiency syndrome (AIDS). "In this work, we could demonstrate that HIV-1 infection and the associated ISG induction correlated with low SRSF1 levels in intestinal lamina propria mononuclear cells (LPMCs) and peripheral blood mononuclear cells (PBMCs) during acute and chronic HIV-1 infection." (PMID 36458014, 2022). "We found that HIV-1 infection induces ciTRAN expression in a Vpr-dependent manner and that ciTRAN interacts with SRSF1, a protein known to repress HIV-1 transcription." (PMID 37672576, 2023). "The RNA sequencing data from SRSF1 wild-type and knockdown cells from a previous study were analyzed to capture a subset of differentially spliced candidates relevant for HIV-1 infection." (PMID 37672576, 2023). "The expression levels of SRSF1 mRNA, which were reduced by 2-fold upon HIV-1 infection, were even elevated by 1.2-fold upon ART treatment when compared to uninfected donors." (PMID 36458014, 2022). "Specific SRSF transcript levels, particularly SRSF1, were significantly lower upon HIV-1 infection." (PMID 36458014, 2022). "Since an inverse correlation between ISG induction and SRSF1 repression has been observed, Vpr could potentially be directly involved in the downregulation of SRSF1 observed upon HIV-1 infection." (PMID 36458014, 2022). "Thus, the strong upregulation of IFN-I and subsequent induction of ISGs during the early inflammation in response to an HIV-1 infection could potentially directly or indirectly result in the repression of SRSF1, suggesting a potential role of SRSF1 as IRepG." (PMID 36458014, 2022). "Thus, suppression of SRSF1 levels, as observed in the early immune response to an HIV-1 infection, could potentially facilitate HIV-1 infectivity and the establishment of a systemic infection." (PMID 36458014, 2022). "The observed lower levels of SRSF1 mRNA transcripts upon HIV-1 infection in LPMCs and PBMCs, as well as the time-dependent downregulation in SRSF1 mRNA in various cell types upon stimulation with IFN-I, suggested SRSF1 to represent an IRepG." (PMID 36458014, 2022). "The determination of Pearson correlation coefficients revealed a negative correlation between ISG15 and SRSF1 mRNA expression upon acute HIV-1 infection." (PMID 36458014, 2022). "We observed a negative correlation between ISG15 and SRSF1 mRNA expression, particularly during acute HIV-1 infection." (PMID 36458014, 2022). "Interestingly, a concomitant HIV-1 infection and IFN stimulation led to rapidly restored SRSF1 levels comparable to PBS-treated cells." (PMID 36458014, 2022).
Infertility (4 papers, 2019 to 2024). "In this study, by crossing Srsf1Floxed/Floxed(Srsf1F/F) mice with Stra8-Cre mice to generate mutant mice with specific deletion of the Srsf1 gene in male germ cells, we found that SRSF1 knockout caused complete infertility and germ cells were drastically lost during spermatogenesis." (PMID 37781512, 2023). "Male germ cell-specific deletion of Srsf1 led to complete infertility by affecting spermatogenesis." (PMID 37781512, 2023). "Subsequently, the breeding experiment indicated that conditional knockout (cKO) mice had a standard mating capacity but that the absence of Srsf1 led to complete infertility in males." (PMID 38271475, 2024).
nasopharyngeal carcinoma (4 papers, 2022 to 2025). A carcinoma arising from the nasopharyngeal epithelium. "In this study, we investigated the mechanism by which EBNA1 interacts with SRSF1 to regulate alternative splicing of host genes, thereby promoting proliferation of nasopharyngeal carcinoma cells." (PMID 40729735, 2025).
Obesity (4 papers, 2018 to 2025). Accumulation of substantial excess body fat. "A small molecule, ABX300, has been identified as a potential therapeutic agent capable of mitigating diet-induced obesity by modulating LMNA isoform expression through the regulation of serine/arginine-rich splicing factor 1 (SRSF1) in HFD-fed mice." (PMID 40732992, 2025). "A small molecule named as ABX300 was identified which can abrogate diet-induced obesity by modulating LMNA isoforms via serine and arginine rich splicing factor 1 (SRSF1) in HFD-fed mice." (PMID 29473878, 2018). "As the amino acid sequences of human and mouse SRSF1 are 100% identical, it is interesting to explore the translational potential of ABX300 in anti-obesity treatment." (PMID 29473878, 2018). "On the other hand, a novel drug targeting the splicing factor SRSF1, ABX300, has been shown to impair SRSF1 splicing activity to treat diet-induced obesity in mice without any observed toxicity." (PMID 35589755, 2022).
schizophrenia (4 papers, 2019 to 2022). A major psychotic disorder characterized by abnormalities in the perception or expression of reality. "Interestingly, GOMAFU can directly interact with the splicing factors quaking (QKI) and SRSF1 (serine/arginine-rich splicing factor 1), and when GOMAFU is dysregulated, the alternative splicing resembles that seen in schizophrenia-associated genes DISC1 and ERBB4." (PMID 31019524, 2019). "The lncRNA GOMAFU can change the AS events of schizophrenia-related genes DISC1 and ERBB4, and GOMAFU can interact with splicing factors QKI and SRSF1, which may be the mechanism of GOMAFU participating in the AS process." (PMID 34750493, 2022).
small cell lung carcinoma (4 papers, 2016 to 2024). Small cell lung cancer (SCLC) is a highly aggressive malignant neoplasm, accounting for 10-15% of lung cancer cases, characterized byrapid growth, and early metastasis. "Meanwhile, SRSF1 copy number gain is associated with DNA repair and chemo-sensitivity, which predicts poor survival in small cell lung cancers (SCLC)." (PMID 36140826, 2022).
chronic lymphocytic leukemia (3 papers, 2015 to 2023). "For instance, SF3B1, SRSF1, U2AF65, and CELF4 are often mutated in chronic lymphocytic leukemia." (PMID 27287018, 2016). "For example, exome-sequencing studies found that SF3B1 was mutated in 10–15% of patients with chronic lymphocytic leukemia, while other spliceosome genes (e.g. SRSF1, SRSF7 and U2AF65) were mutated at lower (but still detectable) frequencies in chronic lymphocytic leukemia patients." (PMID 26498691, 2015).
chronic myeloid leukemia (3 papers, 2023 to 2024). "In chronic myeloid leukemia, overexpression of SRSF1 resulted in impaired imatinib sensitivity via BCR-ABL1 and cytokine-mediated signaling pathways." (PMID 37206090, 2023). "SRSF1 expression was found to be elevated in primary CD34+ progenitors of chronic phase chronic myeloid leukemia (CML) compared to the normal progenitors, which was mediated by BCR-ABL1 and cytokine." (PMID 39034387, 2024).
diabetes (3 papers, 2023 to 2024). "Moreover, when analyzing patients with both PC and diabetes, positive SRSF-1 expression was associated with increased levels of Ki-67 and MVD, suggesting a link between SRSF-1 expression, cell proliferation, and angiogenesis in the context of diabetes-associated PC." (PMID 38731981, 2024).
esophageal cancer (3 papers, 2018 to 2021). A primary or metastatic malignant neoplasm involving the esophagus. "Survival analysis demonstrates that the high expression of HNRNPM and SRSF1 in esophageal cancer might be a poor prognostic marker." (PMID 32903837, 2020).
leukemia (3 papers, 2012 to 2025). A malignant (clonal) hematologic disorder, involving hematopoietic stem cells and characterized by the presence of primitive or atypical myeloid or lymphoid cells in the bone marrow and the blood. "Based on the dataset, we observed that the mRNA level of SFRS1 (encoding SRSF1) was up-regulated in the leukemia cells." (PMID 22839530, 2012). "In addition to the results of our previous study using genome-wide microarray analysis from 100 pediatric ALL cases, we further found that SFRS1 (encoding SRSF1) is up-regulated in leukemia cells." (PMID 22839530, 2012). "Further treatment with the anti-leukemic drugs VCR and Ara-c in leukemia cells resulted in an increase in early apoptosis, which indicated that SRSF1 plays an anti-apoptotic role in chemotherapy." (PMID 22839530, 2012). "It is possible that increased SRSF1 in these leukemia and lymphoma cell lines may interfere with LSV3 expression that would otherwise occur in primary cells of the same type." (PMID 35202654, 2022). "In this study, we found that the SRSF1 or PRMT1 expression levels could be influenced by each other in a leukemia cell line." (PMID 22839530, 2012). "Here, we found that the knock-down of SRSF1 increased the early apoptosis of leukemia cells." (PMID 22839530, 2012). "We also found that expression of SRSF1 and PRMT1 in the Nalm-6 (TEL-AML1 positive) and Reh (TEL-AML1 negative) cell lines could be attenuated with chemotherapy drugs; additionally, SRSF1 and PRMT1 were associated with each other in leukemia cells in vivo." (PMID 22839530, 2012). "Moreover, SRSF1 and PRMT1 were associated with each other in leukemia cells in vivo." (PMID 22839530, 2012). "As an anti-apoptotic factor, over-expression of SRSF1 causes the evasion of apoptosis in leukemic cells, while the knock-down of SRSF1 increases the sensitivity of leukemia cells to the chemotherapy agents, indicating that SRSF1 could potentially become a target for anti-leukemic therapy." (PMID 22839530, 2012). "Moreover, the knock-down of SRSF1 increased the sensitivity of leukemia cells to the chemotherapy agents, suggesting that SRSF1 may be a potential target for anti-leukemic therapy." (PMID 22839530, 2012). "In leukemia, SRPK enhances the splicing regulatory capacity of SRSF1 on cyclin A1 pre-mRNA by phosphorylating SRSF1 at S422, thereby accelerating cell cycle progression and promoting tumor cell proliferation." (PMID 41268214, 2025). "Until now, there has been no relevant report of SRSF1 in leukemia cells." (PMID 22839530, 2012).
metastatic disease (3 papers, 2008 to 2022). "Notably, the same results were observed following Srsf1 knockdown in two mouse CRC organoid lines that model late-stage, metastatic disease." (PMID 35589755, 2022).
multiple myeloma (3 papers, 2022 to 2024). "Enrichment pathway analysis confirmed that SRSF1 takes part in the myeloma progression via tumor-associated and immune-related pathways." (PMID 37206090, 2023). "The expression value of SRSF1 is positively associated with myeloma progression, and high SRSF1 expression might be a poor prognostic biomarker in MM patients." (PMID 37206090, 2023). "We identified SRSF1 as an essential cancer-dependent gene in tumorigenesis by using the DepMap database, especially in multiple myeloma." (PMID 37206090, 2023). "SRSF1 expression showed an increasing trend with the progression of myeloma." (PMID 37206090, 2023). "Across more than 500 lines representing 28 different cancer cell lineages, the dependency scores of SRSF1 in hematological malignancies, especially myeloma, were significantly lower than those in solid tumors, suggesting SRSF1 might play an essential role in hematological malignancies." (PMID 37206090, 2023). "Additionally, the expression level of SRSF1 had a positive correlation with MKI67 expression in MM patients (r = 0.3567, and p < 0.0001), indicating the role of SRSF1 in myeloma development." (PMID 37206090, 2023).
psoriasis (3 papers, 2015 to 2024). An autoimmune condition characterized by red, well-delineated plaques with silvery scales that are usually on the extensor surfaces and scalp. "Further studies on SRSF1 transcriptional regulation will be valuable to determine if SRSF1 is a potential target therapy for psoriasis." (PMID 25658361, 2015). "Finally, we found that SRSF1 levels were downregulated after patients with psoriasis were treated with anti-inflammatory agents, including a TNFα inhibitor." (PMID 25658361, 2015). "To test whether inhibition of TNF-α could suppress SRSF1 expression in patients with psoriasis, we collected PBMCs from patients at weeks 0 and 12 after treatment with adalimumab." (PMID 25658361, 2015). "Notably, SRSF1 expression is downregulated in PBMCs from patients treated for psoriasis." (PMID 25658361, 2015). "Therefore, SRSF1 presents an opportunity for future psoriasis targeted therapies." (PMID 25658361, 2015). "Finally, we sought to determine if SRSF1 has a role in psoriasis." (PMID 25658361, 2015). "Although SRSF1 is downregulated in PBMCs after treatment with adalimumab, we did not observe significant differences in SRSF1 expression in PBMCs between psoriasis patients and healthy donors (data not shown)." (PMID 25658361, 2015).
renal carcinoma (3 papers, 2019 to 2025). A carcinoma arising from the epithelium of the renal parenchyma or the renal pelvis. "In renal cancer 3′-UTR variants of SRSF1 were discovered with differing miRNA target sites, a differential regulation mechanism potentially existing for miR-30c as well." (PMID 37705830, 2023).
asthma (2 papers, 2018 to 2022). "Significant differences in the expression of SRSF1 and SRSF6 were observed between ASM from horses with asthma in exacerbation, when compared to controls." (PMID 30350466, 2018). "For instance, there was a twofold increase on average in the expression of SRSF1 and SRSF6 during exacerbation of equine asthma when compared to controls (P = 0.008)." (PMID 30350466, 2018).
atherosclerosis (2 papers, 2017 to 2021). A disease characterized by the build-up of fatty material and calcium deposition in the arterial wall resulting in partial or complete occlusion of the arterial lumen. "Our present findings not only reveal a novel function of SRSF1 as an activator of VSMC proliferation but also have important implications for a role of SRSF1 in the development of atherosclerosis and perhaps other vascular proliferative disorders." (PMID 28799539, 2017). "Targeting core splicing factors, like SRSF1, using similar strategies in aberrant VSMC proliferation may thereby inhibit the pathogenesis of atherosclerosis and restenosis." (PMID 34638554, 2021).
cardiac hypertrophy (2 papers, 2021 to 2024). "Further studies are underway to investigate whether Miat regulates cardiac RNA splicing through Qki and Srsf1 and what the functions of our identified splicing isoforms are in the pathogenesis of cardiac hypertrophy." (PMID 34335976, 2021).
congenital myasthenic syndrome (2 papers, 2015 to 2024). Congenital myasthenic syndrome (CMS) is a group of genetic disorders of impaired neuromuscular transmission at the motor endplate characterized by fatigable muscle weakness. "The antagonistic regulation of SRSF1 and hnRNP for COLQ exon 16 was part of pathological processes of congenital myasthenic syndrome." (PMID 38922778, 2024).
Dengue (2 papers, 2018 to 2020). "The deficiency in SRSF1 and other RBPs in the nuclei of Influenza, Dengue or SARS-CoV-2 infected cells does not require any specialized mechanism." (PMID 33299552, 2020).
Ewing sarcoma (2 papers, 2020). A small round cell tumor that lacks morphologic, immunohistochemical, and electron microscopic evidence of neuroectodermal differentiation. "In this study, by employing multiple approaches, we have now identified several splicing factors (SRSF1, SRSF3, and SRSF10, hnRNPK, hnRNPM, and FUS) as regulators of DHX9 splicing in Ewing sarcoma cells." (PMID 32023846, 2020).